IL6 (interleukin 6)
Diseases named in the same sentence as IL6 in open-access papers (continued):
Sharing a sentence is not in itself a finding about the gene and the disease.
squamous cell carcinoma (52 papers, 2010 to 2026). A carcinoma arising from squamous epithelial cells. "The relationship between interleukin (IL)-10 and IL-6 gene polymorphisms and squamous cell carcinoma (SCC) has been demonstrated but with inconsistent conclusions." (PMID 37077342, 2023). "The present study assessed the association between IL6 promoter SNPs and squamous cell carcinoma in uranium miners." (PMID 26372664, 2016). "Association between IL-6 promoter single nucleotide polymorphisms (SNPs) and squamous cell carcinoma in miners (odds ratios based on adjusted logistic regression models of 242 cases and 336 controls) and hazard ratios for the time from the onset of high exposure to diagnosis among 162 cases." (PMID 26372664, 2016). "In particular, rs1800797 was associated with increased basal expression and induced secretion of IL-6 by fibroblasts in response to DNA damage in vitro, supporting a role for IL-6 in the association between rs1800797 and squamous cell carcinoma in the former uranium miners." (PMID 26372664, 2016). "There have been some case reports of IL-6-producing thymic carcinoma, including squamous cell carcinoma and undifferentiated thymic carcinoma." (PMID 41374422, 2025). "IL-6 is known to be involved in cell proliferation, immune evasion, and progression of squamous cell cancer." (PMID 36823670, 2023). "Other serum biomarkers such as AFP-L3, DCP, interleukin-6, interleukin-10, and squamous cell carcinoma antigen were also investigated, while these serum-based tests lack adequate sensitivity and specificity for effective surveillance." (PMID 36213826, 2022). "Interleukin 6 (IL-6) and interleukin 8 (IL-8) production in squamous cell carcinoma impaired the activity of NK cells via downregulation of NKp30 and NKG2D receptors." (PMID 35806034, 2022). "In squamous cell carcinoma cells, IL-6 supports cell survival via STAT3 and nuclear factor erythroid 2-related factor 2 signalling." (PMID 36429126, 2022). "Depner and colleagues were able to identify a possible mechanism by which IL-6 activation of stromal fibroblasts contributes to the metastatic potential of human squamous cell carcinoma (SCC)." (PMID 36429126, 2022). "In this context, using squamous cell carcinoma in the proposed in vitro model, the myoepithelial cells appeared to have favored tumor growth via the production of IL-6 and IL-10 stimulated by the malignant cells, in a paracrine way." (PMID 25435982, 2015). "The level of IL-6 was available for eight of the squamous cell carcinoma patients during treatment and so its correlation with CRP, LRG1 and LBP was investigated during radiotherapy." (PMID 26425690, 2015). "The purpose of this study was to investigate the relationship between serum levels of interleukin-6 (IL-6) and the severity and extent of squamous cell carcinoma (SCC) of the larynx based on stage of tumor progression and histological grade." (PMID 26082901, 2015). "Although IL-6 has previously been connected with squamous cell carcinoma bone invasion, which occurs during late stages of the disease, the highest concentration of this cytokine was detected at the beginning of DMBA-treatment." (PMID 23176085, 2012). "An in vitro study on human squamous cell cancer showed that high concentrations of IL-6 will influence the invasion of tumor cells and that metastasis is possible." (PMID 20184737, 2010). "In this regard, a correlation was found between high levels of inflammation cytokines IL-6 and IL-8 in the serum of patients suffering from squamous cell cancer of the H&N as a reaction to stimulation by pro-inflammatory cytokines such as IL-1 and TNF-α." (PMID 20184737, 2010). "Multivariable analysis revealed that squamous cell carcinoma histology (OR = 4.471, 95% CI = 1.037-21.699; P = 0.045) and baseline IL-6 levels ≤5.4 pg/mL (OR = 4.494, 95% CI = 1.089-18.541; P = 0.038) were independently associated with higher odds of achieving an objective response." (PMID 42125658, 2026).
squamous cell carcinoma (continued). "It was demonstrated that the tumor samples of squamous cell carcinoma (SCC) contained high levels of IL‐6, IL‐8, and CXCL1 gene transcripts, a trait that was transferred to normal fibroblasts upon their co‐culture with FaDu carcinoma cells, suggesting paracrine signaling between these cells." (PMID 40621923, 2025). "In the oral mucosa, IL-6 mediated inflammation promotes squamous cell carcinoma through the hypermethylation of Pax6, suggesting epigenetic gene silencing may be an important consequence of chronic inflammation during tumorigenesis." (PMID 24143217, 2013). "In squamous cell carcinoma cell lines, chemerin activates STAT-3 signaling, increasing production of IL-6 and TNF-α, leading to infiltration of neutrophils promoting tumor growth." (PMID 40299651, 2025). "In squamous cell carcinoma, a similar instruction of monocytes to TAM-like myeloid cells was observed and induced through IL-6 and granulocyte and macrophage colony-stimulating factor (GM-CSF) secretion by CAFs." (PMID 39500527, 2024). "IL-6, a key cytokine in the IL-6 family, has been shown to induce the expression of VEGF mRNA in various cancer cell lines, including A431 cells (a human epidermoid carcinoma cell line) and C6 cells (a rat glioma cell line)." (PMID 39759107, 2024). "It has been known that interleukin-6 (IL-6) concentrations are significantly higher in BCC tumor microenvironments compared to other skin cancers, such as squamous cell cancers." (PMID 37902813, 2023). "IL-8 produced by many types of cancers has been demonstrated that significantly secreted by squamous cell carcinoma CSCs, and it can trigger differentiation of Th17 cells through simultaneous activation of STAT3 with IL-6." (PMID 31024835, 2019). "Previous studies in vitro with human cells and squamous cell carcinoma showed that the concentration of certain pro-inflammatory cytokines and pro-angiogenic cytokines, such as TNF-α, IL-1, IL-6 and IL-8, are increased." (PMID 26905729, 2016). "From oral leukoplakia to squamous cell carcinoma, TNF signaling was upregulated, consistent with ELISA results showing progressive increases in IL-6, IL-8, and GROα/CXCL1 in rat serum, indicating the critical role of the inflammatory microenvironment in carcinogenesis." (PMID 41415031, 2025). "Additionally, there was an increase in mean salivary IL-6 levels across different grades of OSCC, with mean values of 43.24 pg/ml for WDSCC, 81.30 pg/ml for moderately differentiated squamous cell carcinoma (MDSCC), and 175.0 pg/ml for PDSCC." (PMID 38803729, 2024). "In this study, we report that the lysates obtained upon sonication or freeze/thawing of oral squamous cell carcinoma cells provoked a robust increase in the expression of interleukins IL1, IL6, and IL8 by gingival fibroblasts, which was confirmed by immunoassays of IL6." (PMID 37391526, 2023). "Additionally, there was an increase in mean salivary and serum IL-6 levels across all grades of OSCC, from well-differentiated squamous cell carcinoma (WDSCC) to poorly differentiated squamous cell carcinoma (PDSCC), as well as across all grades of OED, from mild dysplasia to severe dysplasia." (PMID 38803729, 2024). "Squamous cell carcinomas of head and neck were detected thanks to an ultrasensitive electrochemical immunosensor based on SWNT forests incorporating antibodies to Interleukin-6 (Il-6) and horseradish peroxidase enabling detection of very low and elevated levels of Il-6." (PMID 26579509, 2015).
brain inflammation (51 papers, 2010 to 2025). "The production of large amounts of TNF-α and IL-6 in immune cells is an important factor in causing acute brain inflammation." (PMID 39860162, 2025). "Proinflammatory cytokines like IL-1 and IL-6, triggered by chemotherapy, can infiltrate the CNS from the peripheral immune system, causing localized brain inflammation." (PMID 38406792, 2023). "The direct effect of the activated p38 kinase pathway is the deregulation of inflammation (e.g., reduced levels of TNF-α, IL-1, IL-6, and IL-8) maintaining prolonged brain inflammation." (PMID 40171450, 2025). "TNF-α, IL-1β, and IL-6 are involved in the progression of brain inflammation through inducing the expression of chemokines that facilitate the infiltration of leukocytes into the CNS." (PMID 34765767, 2021). "Several studies reported that in physiological conditions histamine induces both astrocytic and microglia reactivity and increase the release of pro-inflammatory cytokines such as TNFα and IL-6 through H1R and H4R thus sustaining brain inflammation." (PMID 33918940, 2021). "Physical sedentarism is linked to elevated levels of circulating inflammatory markers, such as interleukin-6 (IL-6), a cytokine that increases brain inflammation." (PMID 33810574, 2021). "Brain inflammation often involves expression of IL-1β, IL-6, IL-8, TGF-β1, and TNF-α, thus we started our screening experiments with these commercially available inflammatory factors." (PMID 33013631, 2020). "IL-17 produced by microglia worsens brain inflammation by stimulating GM-CSF production, as well as increasing IL-6, inflammatory proteins, nitric oxide, and adhesion molecule expression by macrophages." (PMID 25431758, 2014). "We also investigated changes in the amount of IL-6, an inflammatory cytokine produced mostly by astrocytes and, to a lesser extent, microglia, during brain inflammation." (PMID 23672668, 2013). "Guy C. Brown found that activation was accompanied by partial rounding up and mobility of the cells, proliferation, and the expression and release of pro-inflammatory cytokines, including TNF-α, IL-1 β, and IL-6 in the event of brain inflammation." (PMID 24236147, 2013). "Additionally, AD is marked by brain inflammation, evidenced by heightened activity in the astrocytes and microglia, along with elevated levels of proinflammatory cytokines such as interleukin-1β, interleukin-6, and tumor necrosis factor-α." (PMID 39932627, 2025). "Moreover, quercetin effectively suppressed the upregulation of Il-8, Il-6, Il-18, and Tnf-α in G. parasuis-infected bEnd.3 cells, thus mitigating the occurrence of brain inflammation." (PMID 38927100, 2024). "We hypothesize that the mechanism by which miR-4763-3p affects apoptosis is related to brain inflammation; therefore, ELISA, IHC and qPCR were performed to evaluate the expression of the inflammatory factors IL-6 and TNF-α in the mouse brain." (PMID 39664587, 2024). "In addition, neuronal loss and microglial activation brought on by LPS-induced brain inflammation caused the release of neurotoxic substances, including inflammatory cytokines (TNF-α and IL-6)." (PMID 36986497, 2023). "Higher levels of peripheral IL-6 were related to brain inflammation." (PMID 34054732, 2021). "Brains were homogenized and intracranial levels of three cytokines known to be associated with and/or causative for HSV-1 mediated brain inflammation and that are also linked with the outcome of HSV-1 encephalitis, IL-6, CCL5 (Rantes) and CCL2 (MCP-1) were measured." (PMID 23082204, 2012). "Pro-inflammatory cytokine levels (IL-1β, IL-6, and TNF-α) in the hippocampus were measured via ELISA to assess brain inflammation in mice." (PMID 41155481, 2025). "Our findings revealed that the serum levels of IL-4, IFN-α, IFN-γ, IL-6, TNF-α, CCL4, P-cadherin, TRAIL, CCL11, and VEGF were significantly higher in cases of brain inflammation compared with brain gliomas." (PMID 39364412, 2024).
brain inflammation (continued). "The current study discovered that diabetic animals with LPS-induced brain inflammation had higher concentrations of TNF-α and IL-6." (PMID 38753370, 2024). "Our results suggest that DOX and MLX exert neuroprotective effects by decreasing proinflammatory cytokine (TNF-α, IL-6 and IL-17) levels and COX-2 synthesis in brain inflammation." (PMID 33149866, 2020). "Brain inflammation activates microglia and leads to the production of proinflammatory molecules such as TNF-α, IL-1β, and IL-6." (PMID 31444225, 2019). "Glial cell and EC responses during infection indicate that soluble molecules, cytokines, and chemokines such as RANTES, TNF-α, IL-6, IL-10, and MCP-1 among others, favor leukocyte infiltration, worsening brain inflammation." (PMID 31293558, 2019). "Altered IL-1β, IL-6, and TNF-α expression levels activating the STAT3 pathway have been found in brain inflammation models." (PMID 28143489, 2017). "IL-17 promotes brain inflammation, inducing the production of pro-inflammatory cytokines, TNF-α, IL-6, and IL-1β most probably from astrocytes, microglia, or macrophages." (PMID 25431758, 2014). "We demonstrate that DMF inhibits a proinflammatory response characterised by increased microglial and astrocytic synthesis of NO, IL-1, IL-6 and TNF-α in an in vitro model of brain inflammation." (PMID 20482831, 2010). "The excessive production of LPS by the gut microbiota triggers the production of inflammatory cytokines such as IL-6, IL-1β, and TNF-α, further disrupting the HPA axis, increasing brain inflammation, and promoting neurodegeneration, which impairs hippocampal neurogenesis." (PMID 40077516, 2025). "ROC analysis of immunological molecules in serum and CSF showed that the expression levels of IL-4, IFN-α, IFN-γ, IL-6, TNF-α, CCL4, CCL11, and VEGF exhibited high sensitivity and specificity in distinguishing between brain inflammation and brain tumor groups (p < 0.05)." (PMID 39364412, 2024). "ELISA data demonstrated that siATP11A significantly increased the expression of IL-6 and TNF-α, while ATP11A overexpression significantly reduced the expression levels of IL-6 and TNF-α, indicating that ATP11A overexpression may alleviate brain inflammation." (PMID 39664587, 2024). "Compared to controls (0.1% BSA in 0.9% NaCl), a significant increase of genes related with glia activation (Gfap and Cd68 but not Iba1) but not with brain inflammation (Il-6, Il-1β) was observed at 24 h post-injection." (PMID 35203276, 2022). "Thus, the results indicate the neuroprotective effect of chondroitin sulfate as an anti-inflammatory agent by suppressing the NF-kB and decreasing the inflammatory mediators (IL-1β, IL-6, and TNF-alpha) that act as biomarkers of brain inflammation." (PMID 34833865, 2021). "We have shown that P. gingivalis periodontal infection may induce an age-dependent brain inflammation, which increases the TNF- α, IL-6, and IL-1 β levels in middle -aged mice." (PMID 29422938, 2018). "Consistent with the results of in vitro experiments, an LPS-induced brain inflammation mouse model, administration of TEC effectively decrease the levels of malondialdehyde, iNOS in hippocampus, and prevented increases in the levels of TNF-α and IL-6 in the serum." (PMID 29867470, 2018). "In addition, the mRNA expression levels of inflammatory cytokines (Il-6, Il-8, Il-10, Il-18, Il-1β, and Tnf-α) in GPS-infected mice were significantly increased compared to the control group (p < 0.05), which indicated that GPS successfully induced brain inflammation in mice." (PMID 38927100, 2024).
hypertriglyceridemia (51 papers, 2011 to 2025). A laboratory test result indicating elevated triglyceride concentration in the blood. "Severe hypertriglyceridemia in the HHTg rats was associated with low-grade chronic inflammation, characterized by significantly elevated serum levels of leptin, IL-6, and PAI-1." (PMID 39858414, 2024). "IL-6 is also associated with hypertriglyceridemia and the anti-inflammatory cytokine." (PMID 33671547, 2021). "Like TNF-α, IL-6 is also associated with hypertriglyceridemia." (PMID 24733068, 2014). "Hypertriglyceridemia promotes a state of low-grade systemic inflammation, characterized by an increase in proinflammatory cytokines, such as interleukin-6 (IL-6), tumor necrosis factor-alpha (TNF-α), and C-reactive protein (CRP)." (PMID 41149060, 2025). "Increased concentrations of IL-6 contribute to hypertriglyceridemia and increased LDL cholesterol levels by inhibiting hepatic lipoprotein lipase activity, stimulating triglyceride synthesis, and enhancing lipolysis in adipose tissue." (PMID 40283183, 2025). "Blood levels of glucose, lactate dehydrogenase, C-reactive protein (C-RP), procalcitonin, ferritin, interleukin (IL)-6 were higher in patients with hypertriglyceridemia." (PMID 38449886, 2024). "IL-6 has been found to trigger hypertriglyceridemia through the stimulation of lipolysis and hepatic triglyceride secretion in sedentary animals and humans." (PMID 36434695, 2022). "When metabolic disorders occur, the levels of postmeal glucose, C-reactive protein (CRP), and inter-leukin-6 (IL-6) increase; hypertriglyceridemia ensues and the levels of apolipoprotein A1 and HDL cholesterol decrease." (PMID 34769939, 2021). "The pro-inflammatory molecules can affect the host metabolic process, as TNF-α was reported to decrease the insulin sensitivity and increase lipolysis in adipocytes, as well as IL-6 was found to contribute to hypertriglyceridemia." (PMID 32256675, 2020). "A previous study showed that elevated serum IL-6 induces hypertriglyceridemia, which manifests before the deposition of beta amyloid (Aβ) in AD." (PMID 22272811, 2012). "Similarly, another cross-sectional study also found that MS patients with hypertriglyceridemia had a significant increase in plasma IL-6 levels, and that IL-6 was positively correlated with HOMA-IR." (PMID 33692759, 2021). "Hypertriglyceridemia and upregulated serum TG subjects produce high levels of IL-6 and TNF-α." (PMID 33671547, 2021). "In addition, TNF-α can reduce the activity of lipoprotein lipase and IL-6 increase the uptake of fatty acids to adipose tissue and to the liver, which in turn promotes hypertriglyceridemia." (PMID 32187268, 2020). "Furthermore, IL-6 neutralizing antibody Actemra (tocilizumab) induces body weight gain, hypertriglyceridemia, and hypercholesterinemia in humans." (PMID 30134607, 2018). "Moreover, long-term administration of humanized anti-IL-6 antibody Actemra (tocilizumab) results in hypertriglyceridemia in human subjects and the severity appears to increase in a time-dependent manner." (PMID 30134607, 2018). "After adjusting for age, gender (model 2) and additionally controlling for smoking status, alcohol drinking, tea drinking, high-sensitivity C-reactive protein (hsCRP) and interleukin-6 (IL6), associations of BCAAs with MetS and hypertriglyceridemia were also present (Ptrend < 0.05; model 3)." (PMID 29179484, 2017). "Subjects with hypertriglyceridemia have a higher production capacity of IL-6 as well as TNF-α, and increased levels of serum triglycerides are associated with increased levels of IL-6." (PMID 24733068, 2014). "TNF alpha and IL-6 also suppress lipoprotein lipase synthesis in adipose tissue, which may contribute to hypertriglyceridemia and the low HDL-cholesterol concentrations observed in individuals with intra-abdominal obesity." (PMID 23526980, 2013).